MTDH (metadherin)
Diseases named in the same sentence as MTDH in open-access papers (continued):
Sharing a sentence is not in itself a finding about the gene and the disease.
breast carcinoma (continued). "MTDH is expressed in various types of cancers other than breast cancer cells and is known to be involved in cancer malignancy." (PMID 34445736, 2021). "Immunohistochemical staining was applied to detect MTDH expression in tissues of breast cancer patients and adjacent tissues, and we found that MTDH expression in cancer tissues was significantly higher than that in adjacent tissues." (PMID 34552061, 2021). "Metadherin (MTDH), first identified in primary human fetal astrocytes by rapid subtraction hybridization and named AEG-1, is a well-known oncogene in various cancers, including head and neck cancer, lung cancer, liver cancer, breast cancer, and melanoma." (PMID 34622157, 2021). "In MCF-7 cells, SP-1 (at 100, 200, and 400 μg/mL) induced apoptosis through increasing Bax expression and decreasing MTDH levels, which is frequently upregulated in various human tumor types, including breast cancer." (PMID 34200897, 2021). "TCGA data analysis showed that MTDH was high-expressed in the breast cancer tissues and this was related to a poor prognosis." (PMID 34552061, 2021). "Upstream of TWIST1, Metadherin (MTDH) was shown to epigenetically activate TWIST1 to promote stem-like traits in breast cancer." (PMID 34277708, 2021). "And the study results found that miR-9-3p can inhibit the biological function of breast cancer cells regulated by the MTDH gene and affect the growth and drug resistance of breast cancer cells." (PMID 34552061, 2021). "The study proved that miR-9-3p regulates biological functions, drug resistance, and the growth of Gem-treated breast cancer cells through targeting MTDH." (PMID 34552061, 2021). "High-expressed MTDH in many malignant tumors such as breast cancer, liver cancer, prostate cancer, and glioma has been found to be related to cancer prognosis." (PMID 34552061, 2021). "At the same time, we detected the expression of MTDH in breast cancer cell lines, and found that MTDH was the highest in MCF7 cells but the lowest in HCC1806 cells." (PMID 34552061, 2021). "In this study, by examining breast cancer tissues, we found that the expression of MTDH in the cancer tissues was significantly increased." (PMID 34552061, 2021). "Other targets of miR-30a in breast cancer have also been identified as potential links between this miRNA and the regulation of metastatic progression, including vimentin, MTDH, and Eya2." (PMID 32309442, 2020). "Metadherin (MTDH) is regarded as a key factor implicated in promoting metastasis in various malignancies, including breast cancers, esophageal cancers, gliomas, bladder cancers, and HCC14,15." (PMID 32968053, 2020). "Metadherin (MTDH), which is also named as astrocyte-elevated gene-1 protein (AEG-1), was an up-regulated gene in breast cancer." (PMID 31912882, 2020). "The expression of MTDH in breast cancer is related to the poor pathological features, poor prognosis, and chemo-resistance." (PMID 33003428, 2020). "Cox regression analysis further indicated a prognostic significance of MTDH and IL-10 expression, age, and stage on five-year overall survival period in breast cancer." (PMID 33003428, 2020). "Overexpression of MTDH has been reported in many cancer types, including liver, prostate, colorectal, glioblastoma, and breast cancers." (PMID 31979093, 2020). "With regard to MTDH and IL-10 protein expression status for using univariate and multivariate analysis, the results showed that the protein expression of MTDH and IL-10 in ER-negative or PR-negative breast cancer patients have the worse prognosis." (PMID 33003428, 2020). "The positive correlation of MTDH with poor prognosis in breast cancer patients suggests that MTDH is an ideal target for chemotherapy." (PMID 31979093, 2020). "The exact mechanism and functional significance of MTDH-mediated glycolysis and metastasis in breast cancer remains to be investigated further." (PMID 33003428, 2020).
breast carcinoma (continued). "Our present study indicates that MTDH is related to aggressive phenotypes and a poor prognosis; hence, it is a potential target for anticancer drugs in breast cancer." (PMID 33003428, 2020). "Online data analysis using cBioPortal and GEPIA 2 showed an increased MTDH expression in breast cancer tissues, including the TNBC subtype (p < 0.05)." (PMID 32074085, 2020). "Kaplan–Meier plot analysis revealed a correlation between higher levels of MTDH and shorter lifetimes in breast cancer and TNBC patients." (PMID 31979093, 2020). "In our cohort involving 265 breast cancer patients, MTDH and IL-10 expression significantly correlated with clinically characteristic ER and PR status." (PMID 33003428, 2020). "More studies on the mechanism and functional significance of MTDH- and IL-10 mediated breast cancer progression are warranted." (PMID 33003428, 2020). "Surely, MTDH also functions in several aspects of breast cancer, mainly including tumor cell proliferation, apoptosis, angiogenesis, chemoresistance and metastasis." (PMID 32993809, 2020). "In conclusion, for the first time the miR-128/MTDH, a functional metastamir-oncogene pair, was proved to be a crucial regulator of breast cancer metastasis." (PMID 32993809, 2020). "Meanwhile, the protein expressions of MTDH and IL-10 were positively correlated in our breast cancer cohort (R = 0.442, p < 0.001, n = 265)." (PMID 33003428, 2020). "Ectopic expression of miR-128 can impair migration and invasion capacity of breast cancer cell by directly targeting MTDH, which makes “miR-128/MTDH” a potential contributory “metastamir-oncogene” pair for developing target therapy in the future." (PMID 32993809, 2020). "MTDH is an oncoprotein in numerous human tumorigeneses, including lung, colon, head and neck, liver, glioma, and breast cancers." (PMID 33003428, 2020). "Kaplan–Meier plot analysis was performed to examine the correlation between MTDH expression and the survival rates of breast cancer and TNBC patients." (PMID 31979093, 2020). "Functional study demonstrated that ectopic expression of miR-128 significantly suppressed migration and invasion capacity of breast cancer cells by directly targeting oncogene MTDH." (PMID 32993809, 2020). "On the basis of previous evidence, up-regulation of MTDH frequently occurred in multiple cancers, such as melanoma, breast cancer, and prostate cancer and the behavior of MTDH overexpression was also related to poor clinical outcome." (PMID 31912882, 2020). "For example, MTDH in breast cancer down regulates expression of the PTEN (Phosphatase and tensin homolog) tumor suppressor via NF-κB mediated pathways and contributes to the HER2-targeting therapy resistance." (PMID 31131259, 2019). "In vitro forced overexpression of FBXW7 repressed breast cancer cell proliferation and promoted apoptosis by targeting the oncoprotein, metadherin (MTDH) for proteolysis." (PMID 30791487, 2019). "This review will discuss some recent progresses about the alternative splicing regulators such as CD44, heterogeneous nuclear ribonucleoprotein M (hnRNPM), SND1 and MTDH etc. in breast cancer metastasis." (PMID 31737791, 2019). "MTDH was reported as an oncogene in several cancer types, such as glioma, neuroblastoma, breast cancer, prostate cancer, liver and oesophagus cancer, especially mucosal melanoma." (PMID 31118065, 2019). "Only the enforced expression of MTDH in this amplified 8q22 region was identified to increase lung seeding after tail vein injection of the mildly metastatic breast cancer cell line MDA-MB-231." (PMID 31737791, 2019). "Expression of miR-26a regulates MTDH levels, where the loss of miR-26a in triple negative breast cancer cells (TNBC) leads to increased MTDH and acts as a prognostic marker for breast cancer outcome." (PMID 31131259, 2019). "Overexpression of MTDH and SND1 in primary tumors is strongly associated with reduced metastasis-free survival in multiple large-scale datasets of breast cancer patients." (PMID 31737791, 2019).
breast carcinoma (continued). "Previous study showed that overexpression of MTDH induces estrogen-independent growth of MCF-7 breast cancer cells and mediates tamoxifen resistance." (PMID 30227879, 2018). "For instance, epigenetic activation of twist family bHLH transcription factor 1 (TWIST1) by metadherin (MTDH) promotes cancer stem-like cell traits in breast cancer." (PMID 30231942, 2018). "In summary, we have revealed, for the first time, that overexpression of MTDH in breast cancer cells is related to TAX chemotherapeutic drug resistance." (PMID 30227879, 2018). "We now study how the MTDH expression in MCF-7 cell affects the effectiveness of the TAX drug treatment on breast cancer." (PMID 30227879, 2018). "Based on these MTDH gene-associated clinical characteristics, we conducted the subsequent study to confirm the function of MTDH gene in breast cancer and its possible relationship with TAX chemotherapy." (PMID 30227879, 2018). "Based on our study, we provide a new strategy for reversing TAX resistance in breast cancer treatment, especially for those with high MTDH protein level." (PMID 30227879, 2018). "Using lentiviral vector-mediated gene knockdown, we first demonstrated that TAX therapeutic efficiency was closely correlated with metadherin (MTDH) gene expression in breast cancer cell lines." (PMID 30227879, 2018). "This implies that one can increase the effectiveness of TAX treatment on breast cancer by lowering MTDH expression in tumor cells." (PMID 30227879, 2018). "In our study cohort of 44 patients with breast cancer, we found that MTDH expression was negatively correlated with the probability of DFS and efficacy of TAX treatment, which should be further confirmed in a large population of patients with breast cancer." (PMID 30227879, 2018). "To investigate the effect of MTDH expression in breast cancer cell lines, we first performed RT-PCR tests on our modified MCF-7 breast cancer cells." (PMID 30227879, 2018). "In our study, we further confirmed that MTDH was upregulated in breast cancer cell lines and tissues." (PMID 29088804, 2017). "In the field of oncology, MTDH was initially identified as a regulator for metastasis in breast cancer cells." (PMID 29029495, 2017). "We’ve previously found that MTDH was up regulated in breast cancer and overexpression of MTDH promoted TNBC cell growth and metastasis." (PMID 29088804, 2017). "Our findings clearly demonstrate that miR-320a suppresses breast cancer metastasis by directly inhibiting MTDH expression." (PMID 27229534, 2016). "MiR-630 mimics rather than miR-NC suppressed the luciferase activity of reporter genes containing WT-3′UTR of these genes to some degree, whereas only the activity of 3′UTR of MTDH was reduced significantly in BT-549 breast cancer cells." (PMID 26595523, 2016). "The 18FDG-AuNPs-Anti-MTDH conjunction was co-incubated with breast cancer MCF7 cells and an apoptosis rate of 20% was observed, compared with the 2% in the control." (PMID 27056889, 2016). "Metadherin (MTDH) is identified as an oncogene in multiple cancers including breast cancer, bladder cancer and endometrial cancer." (PMID 26683226, 2016). "Herein, we report that miR-630 is significantly suppressed in human breast cancer specimens and cancer cell lines, and the miRNA suppresses breast cancer progression by targeting metadherin (MTDH)." (PMID 26595523, 2016). "These phenomenon suggest that the functional importance of MTDH-miR-630 makes it a potential therapeutic target in breast cancer treatment." (PMID 26595523, 2016). "Other studies demonstrated that high level MTDH expression predicted poor survival of patients with esophageal squamous cell carcinoma and breast cancer." (PMID 27765924, 2016). "The pooled results suggested that high level of MTDH significantly predicted distant metastasis and lymph node metastasis in breast cancer." (PMID 27917902, 2016).
breast carcinoma (continued). "MTDH is located at chromosome region 8q22, a frequently amplified region in clinical breast cancers, promotes breast cancer development by enhancing chemoresistance and tumor cell adhesion to endothelial cells." (PMID 26595523, 2016). "In this study we revealed MTDH was the executor of pathology functional of miR-630, mediated the functions of miR-630 on suppressed migration and invasion or colony formation of breast cancer cells." (PMID 26595523, 2016). "Downregulation of miR-320a would result in the MTDH overexpression which contributes to the progression of breast cancer." (PMID 27229534, 2016). "To evaluate the clinical significance of MTDH expression in breast cancer, we analyzed the relationship between MTDH expression and the clinicopathologic characteristics." (PMID 27229534, 2016). "The results further demonstrated that MTDH is involved in pathological actions of miR-630 in breast cancer metastasis." (PMID 26595523, 2016). "A more direct indicator of cancer progression, MTDH is an oncogene which promotes breast cancer cell proliferation." (PMID 26917087, 2016). "Anti-metadherin (anti-MTDH) antibodies which are specific to breast cancer cells, were bound to AuNPs via [18F]2-fluoro-2-deoxy-d-glucose (18F-FDG)." (PMID 27056889, 2016). "In order to further investigate the contribution of MTDH to the migration, invasion and colony formation, miR-NC or mature miR-630 was cotransfected with MTDH expression plasmid or its related vector respectively into breast cancer cells." (PMID 26595523, 2016). "The present study provides a new insight into anti-oncogenic roles of miR-320a and suggests that miR-320a/MTDH pathway is a putative therapeutic target in breast cancer." (PMID 27229534, 2016). "In order to confirm the role of MTDH in the sensitivity of breast cancer cells to doxorubicin, we designed three different short-hairpin RNA constructs (MTDH-siRNA1, MTDH-siRNA2, and MTDH-siRNA3) to knock down MTDH in MCF-7/ADR cell line." (PMID 25993398, 2015). "Microarray analysis in breast cancer cells revealed that knockdown of MTDH led to decreased expression of chemoresistance genes ALDH3A1, MET, HSP90, and HMOX1 and increased expression of proapoptotic genes BNIP3 and TRAIL." (PMID 25993398, 2015). "The mRNA and protein expression of MTDH were determined by real-time PCR and Western blot in breast cancer cells such as MDA-MB-231, MCF-7, MDA-MB-435S, MCF-7/ADR cells." (PMID 25993398, 2015). "Although a large number progresses have already been made, the change in the expression of MTDH in breast cancer cells with different molecular phenotypes, and its impact on drug resistance to anthracyclines are still unclear." (PMID 25993398, 2015). "In the present study, MTDH expression in breast cancer MCF-7/ADR cells was down-regulated by siRNA interference, and cell proliferation was obviously inhibited after silencing." (PMID 25993398, 2015). "Up-regulating MTDH expression can promote the proliferation of many tumor cell lines including esophageal cancer, gastric cancer, glioma, and breast cancer." (PMID 25993398, 2015). "The mRNA expression of MTDH gene in breast cancer cells revealed an increasing trend from low to high level, as 1.11 ± 0.10 in MDA-MB-231 cells, 17.58 ± 3.11 in MCF-7 cells, 49.66 ± 10.77 in MDA-MB-435S cells, and 201.74 ± 14.57 in MCF-7/ADR cells." (PMID 25993398, 2015). "Previous studies have demonstrated that knockdown of the MTDH gene led to an increase in breast cancer cell sensitivity to paclitaxel, doxorubicin and cisplatin." (PMID 25684730, 2015). "Overexpression of MTDH has been observed in multiple types of cancer, including breast cancer, hepatocellular carcinoma, human glioma, neuroblastoma, esophageal cancer, non-small-cell lung cancer, cervical cancer and PC." (PMID 25684730, 2015). "Since 2004, MTDH has been considered a potential mediator of cancer metastasis involving lung metastases from breast cancer." (PMID 25684730, 2015).
breast carcinoma (continued). "In order to further validate the role of MTDH in the resistance of breast cancer cells to doxorubicin, the MDA-MB-231 cell line with overexpressed MTDH revealed the enhanced expression of both mRNA and protein levels." (PMID 25993398, 2015). "In summary, MTDH is a proto-oncogene expressed differentially in breast cancer cells with different molecular features." (PMID 25993398, 2015). "We examined the expression of MTDH in four different types of breast cancer cell lines and tested their sensitivity to doxorubicin." (PMID 25993398, 2015). "Taken together, these results strongly suggest that MTDH expression contributes to the resistance of breast cancer cells to doxorubicin." (PMID 25993398, 2015). "The aim of this study is to determine the change of MTDH expression in breast cancer cells with different molecular phenotypes, and its relationship with doxorubicin resistance." (PMID 25993398, 2015). "Our studies have demonstrated that MTDH expression in 4 types of breast cancer cells was different, and revealed an ascending order as MDA-MB-231 (ER-, PR-, HER-2-), MCF-7 (ER+, PR+, HER-2-), MDA-MB-435S (ER-, PR-,) and MCF-7/ADR." (PMID 25993398, 2015). "Expression of MTDH and miR-375 were inversely correlated in primary breast cancer samples, and survival data from tamoxifen-treated patients revealed that higher expression of MTDH was associated with a shorter disease-free survival and higher risk of relapse." (PMID 25849966, 2015). "As a recognized cancer gene, MTDH plays important roles in the onset and development of breast cancer and many other tumors." (PMID 25993398, 2015). "In order to explore the association between metadherin (MTDH) and doxorubicin sensitivity, the differential expressions of MTDH in breast cancer cell lines and the sensitivity to doxorubicin of breast cancer cell lines were investigated." (PMID 25993398, 2015). "Previous immunohistochemical analysis of pathological sections from 225 patients with breast cancer has demonstrated high expression of MTDH in 44.4% of cases and the expression level of MTDH is positively correlated with the degree of malignancy." (PMID 25993398, 2015). "Currently, a large number of experiments have confirmed that the MTDH gene can be used as a biomarker to evaluate the prognosis of breast cancer." (PMID 25993398, 2015). "In consistence with previous findings, clinical data in this study revealed high MTDH but low PTEN expressions in HER2 positive breast cancer tissues, and MTDH overexpression was related with advanced pathological stage and Ki-67 index." (PMID 25417825, 2014). "These two genes, MTDH and HMGA2, are known as oncogenes in a variety of human cancers; MTDH protein is over-expressed and promotes metastatic seeding in breast cancer and over-expression of HMGA2 also induces metastasis and invasion of human cancer cells." (PMID 25340791, 2014). "Results of immunohistochemical studies from several groups reveal diverse MTDH expressions in HER2 positive breast cancer tissues (ranging from 39% to 65%), emphasizing the potential role of MTDH in tumor progression." (PMID 25417825, 2014). "These evidence supported that MTDH participated in the alteration of trastuzumab resistance via modulating PTEN expression in HER2 positive breast cancer cells." (PMID 25417825, 2014). "The 8q22 region was recently shown to harbor the metastasis gene, MTDH, which was overexpressed and amplified in poor-prognosis breast cancer." (PMID 23936250, 2013). "Copy number gain at 8q22 has also been shown to correlate with increased expression levels of several genes across this region, including MTDH, LAPTM4B and YWHAZ, and associated with poor clinical outcome for breast cancer patients." (PMID 23936250, 2013). "MiR-26a has been reported as a tumor suppressor microRNA in breast cancer, which is attributed mainly to targeting of MTDH and EZH2, however, the expression profile and therapeutic potential of miR-26a is still unclear." (PMID 23750239, 2013).